SSBP2 (single stranded DNA binding protein 2)
Diseases named in the same sentence as SSBP2 in open-access papers (continued):
Sharing a sentence is not in itself a finding about the gene and the disease.
oropharyngeal carcinoma (1 paper, 2016). Carcinoma, predominantly squamous cell, arising from the epithelial cells of the oropharynx. "The similarity in the frequency and localization of LMO4, LDB1, and SSBP2/3 expression in oral cavity and oropharyngeal carcinomas, by contrast, suggest these proteins subserve common functions in HNSCC regardless of etiology." (PMID 27780223, 2016).
Polycythemia Vera (1 paper, 2013). "Mutation of JAK2 is observed in several hematological disorders including ET, Polycythemia Vera, Primary Myelofibrosis and Acute Lymphoid Leukemia (ALL) as well as chromosomal translocations involving the fusion partners TEL, BCR, PCM1, PAX5, SEC 31A and SSBP2." (PMID 24086539, 2013).
prostate tumors (1 paper, 2017). "Among other genes tested, we have previously reported 61% promoter methylation of SSBP2 in prostate tumors." (PMID 28147335, 2017).
tumor (13 papers, 2010 to 2024). "Loss of nuclear SSBP2 expression was significantly correlated with larger tumor size, higher histological grade, higher pT stage, ER status, and molecular subtype." (PMID 35204577, 2022). "SSBP2 is ubiquitously expressed and the loss of its expression has been reported in various tumor types." (PMID 33339271, 2020). "SSBP2 expression was associated with tumor invasiveness in SCC." (PMID 37509458, 2023). "The univariate survival analysis for OS showed that SSBP2 expression, age, sex, pT category, nodal status, stage, histologic grade, lymphatic invasion, vascular invasion, perineural invasion, and tumor budding were significantly associated with OS (p < 0.05 for all cases)." (PMID 33339271, 2020). "SSBP2 acts as a tumor suppressor by responding to DNA damage and promoting cell growth arrest by blocking the Wnt signaling pathway." (PMID 37987361, 2023). "Single-stranded DNA binding protein 2 (SSBP2) is ubiquitously expressed, with several studies reporting it to be a tumor suppressor." (PMID 32745119, 2020). "SSBP2 expression was investigated by immunohistochemistry, and positive expression was defined as more than 10% of the tumor cells to show nuclear staining." (PMID 30541499, 2018). "SSBP2 positivity was more frequently observed in cases with tumor multifocality, higher histologic grade, and vascular invasion." (PMID 30541499, 2018). "Positive SSBP2 expression was significantly correlated with tumor multifocality (P = 0.027, chi-square test), high histologic grade (P = 0.003, chi-square test), and frequent vascular invasion (P = 0.001, chi-square test)." (PMID 30541499, 2018). "A total of 15 genes (AIM1, ARF, CCNA1, MGMT, hMLH1, PGP9.5, S100A2, APC, RAR-β2, ER-α, ER-β, MCAM, VGF, FKBP4 and SSBP2) were analysed for promoter methylation using QMSP in 57 tumour samples, comprising 43 SEs and 14 NSEs, and 23 NT samples." (PMID 22068818, 2012). "Our previous studies reported that Sequence Specific Binding Protein 2 (SSBP2), a candidate tumor suppressor is recruited to aggresomes in adenovirally transformed human embryonal kidney 293 (HEK293) cells." (PMID 20540776, 2010). "Additionally, our findings highlighted the association of ZMIZ1 with key factors involved in tumor progression, such as MMP7, MKP-1, and SSBP2, underscoring its multifaceted impact on TSCC biology." (PMID 38866828, 2024). "Single-stranded DNA binding protein 2 (SSBP2) is a tumor suppressor candidate." (PMID 37509458, 2023). "Regarding whether SSBP2 function is a tumor suppressor or tumor promoter, its exact role remains unclear." (PMID 35204577, 2022). "Previous studies have suggested that SSBP2 has a tumor suppressor function or oncogenic function." (PMID 35204577, 2022). "Recently, some studies have suggested that SSBP2 shows a tumor suppressor function in human cancer." (PMID 35204577, 2022). "Further investigation is needed to clarify the role of SSBP2 in tumor proliferation." (PMID 30541499, 2018). "The tendency to reverse EMT indicates that SSBP2 may play an important role in tumor invasion and distant metastasis." (PMID 30541499, 2018). "The role of SSBP2 in solid organ tumors is still under investigation, with the results of previous studies being inconsistent as to whether SSBP2 functions as a tumor promoter or suppressor." (PMID 30541499, 2018). "SSBP2 acts as a tumor suppressor and may be used as a CRC prognostic biomarker." (PMID 33339271, 2020). "Expression levels of Jagged1, MKP-1, MMP7, Notch1, SSBP2, and ZMIZ1 in tumor tissues of LV-ZMIZ1-RNAi CAL-27 mice were decreased compared to the control group (P < 0.05)." (PMID 38866828, 2024). "Expression of invasion and metastasis-related proteins MKP-1, MMP-7, and SSBP2 were also significantly increased in TSCC tumor tissues, consistent with a propensity of tumor cells to metastasize." (PMID 38866828, 2024).
tumor (continued). "To further evaluate the role of SSBP2 in tumor cell invasion, we performed a Transwell invasion assay in normal HCC cell lines and HCC cell lines (Huh7) transfected with SSBP2 siRNA." (PMID 30541499, 2018). "Sixteen primary matched tumor and serum were analyzed by quantitative methylation specific PCR (QMSP) to determine analytical and clinical sensitivity of the genes tested (SSBP2, MCAM, ERα, ERβ, APC, CCND2, MGMT, GSTP1, p16 and RARβ2)." (PMID 28147335, 2017). "Here, we implicate two LDB1-binding proteins, single-stranded binding protein 2 (SSBP2) and 3 (SSBP3), in controlling LMO4 and LDB1 protein abundance in HNSCC and in regulating specific tumor cell functions in this disease." (PMID 27780223, 2016). "Prognostic significance of CD5 expression in SSBP2+ and SSBP2− DLBCL patients also suggests a tumor-suppressor function of SSBP2 for CD5 signaling." (PMID 25760242, 2015). "Single-stranded DNA binding protein 2 (SSBP2) is involved in DNA damage response and may induce growth arrest in cancer cells, having a potent tumor suppressor role." (PMID 33339271, 2020). "SSBP2 was more frequently expressed in HCC tumor tissues compared to normal liver or adjacent non-neoplastic tissues (P < 0.001, chi-square test for linear trend)." (PMID 30541499, 2018). "Interestingly, SSBP2 expression abolished the prognostic significance of CD5 expression, suggesting a tumor-suppressor role of SSBP2 for CD5 signaling." (PMID 25760242, 2015). "Whether SSBP2 is a tumor suppressor or tumor promoter is still unclear, and there is no consensus on the exact role of SSBP2 expression in human malignancies." (PMID 35204577, 2022). "Although there are several studies describing SSBP2 as a regulator of cell cycle by C-MYC regulation in myelomonocytic cells, there is not yet a confirmative study disclosing the specific molecular pathway and function of the SSBP2 protein in tumor cell proliferation in solid organs." (PMID 30541499, 2018). "No aberrant methylation (i.e., hypermethylation) was detected in the serum of PC patients who did not also have aberrant methylation of the same promoter in the corresponding tumor sample with one exception for SSBP2, where methylation was detected in serum but not in tumor." (PMID 28147335, 2017). "Interestingly, CD30 and SSBP2 (a tumor-suppressor) expression was frequently negative in CD5+ DLBCL patients." (PMID 25760242, 2015). "For the remaining genes (SSBP2, MCAM, ERα, ERβ, CCND2, MGMT, GSTP1 and p16) methylation in serum DNA was always corresponding to methylation of tumor DNA, while methylation of tumor DNA was not always corresponding to methylation of serum DNA." (PMID 28147335, 2017).
cancer (11 papers, 2009 to 2023). A tumor composed of atypical neoplastic, often pleomorphic cells that invade other tissues. "Analysis of surviving Ssbp2 null mice at 60–80 weeks of age revealed that in addition to formation of carcinomas and lymphomas in multiple organs, chronic glomerular nephropathy was a significant finding in these mice." (PMID 37794075, 2023). "The role of SSBP2 in cancer development and cancer progression appears to vary with the type of malignant tumor." (PMID 35204577, 2022). "By contrast, SSBP2, a gene involved in DNA and telomere repair and growth arrest of cancer cells was also found to be upregulated in ASD LCLs." (PMID 35743705, 2022). "The seven TFs downregulated by Wnt inactivation were all upregulated in cancer, and two of the four TFs upregulated by Wnt inactivation (HIS1 and SSBP2) were downregulated in cancer." (PMID 19156145, 2009). "Further investigation is needed to clarify the cancer-specific mechanism of SSBP2." (PMID 30541499, 2018). "The effect of SSBP2 on the carcinogenesis and progression of malignant tumors is not yet clear." (PMID 32745119, 2020).
SSBP2 also shares sentences with these, for which no sentence is quoted: benign prostatic hyperplasia (4 papers); gallbladder cancer (3); adenocarcinoma (2); hematologic malignancies (2); Myelodysplasia (2); clear cell renal cell carcinoma (1); endothelial dysfunction (1); lung carcinoma (1); lymphoma (1); oligodendroglial tumours (1); primary myelofibrosis (1); skin cancer (1); squamous cell carcinoma (1).